IL26 (interleukin 26)
Description:
May play a role in local mechanisms of mucosal immunity and seems to have a pro-inflammatory function. May play a role in inflammatory bowel disease. Activates STAT1 and STAT3, MAPK1/3 (ERK1/2), JUN and AKT. Induces expression of SOCS3, TNF and IL-8, secretion of IL-8 and IL-10 and surface expression of ICAM1. Decreases proliferation of intestinal epithelial cells. Is inhibited by heparin.
Synonyms: IL-26; AK155
Tractability: Antibody: UniProt places it where antibodies can reach, with high confidence; its Gene Ontology location is reachable by antibodies, with high confidence; UniProt predicts a signal peptide or a membrane-spanning region.
Gene: Protein-coding gene on chromosome 12 (68,201,349 to 68,225,810, reverse strand). Ensembl gene ENSG00000111536.
Subcellular location: Secreted
Subcellular location (Human Protein Atlas): Golgi apparatus; Vesicles; Predicted to be secreted
Pathways (Reactome):
Immune System: Interleukin-20 family signaling
Gene Ontology:
Molecular function: cytokine activity
Biological process: negative regulation of epithelial cell proliferation; positive regulation of cytokine production; positive regulation of ERK1 and ERK2 cascade; positive regulation of phosphatidylinositol 3-kinase/protein kinase B signal transduction; positive regulation of receptor signaling pathway via JAK-STAT; positive regulation of stress-activated MAPK cascade; positive regulation of transcription by RNA polymerase II; cell surface receptor signaling pathway via JAK-STAT; cell-cell signaling; defense response to bacterium; immune response; inflammatory response
Cellular component: cytosol; extracellular region; receptor complex
Genetic constraint (gnomAD): Loss-of-function variants: 8 observed, 10.67 expected, observed/expected ratio (o/e) 0.75, 90% interval 0.44 to 1.35. The upper end of that interval is the gene's LOEUF score, 1.35, which puts it in group 5 of 6, group 1 being the genes least tolerant of losing a copy. Missense variants: 115 observed, 122.79 expected, observed/expected ratio (o/e) 0.94, 90% interval 0.8 to 1.09. Synonymous variants: 38 observed, 46.59 expected, observed/expected ratio (o/e) 0.82, 90% interval 0.63 to 1.07.
Homologues: Orthologues: chimpanzee IL26 (100% identical), macaque IL26 (95% identical), pig IL26 (85% identical), dog IL26 (81% identical), rabbit IL26 (71% identical). Paralogues in human: IL10 (25% identical), IL24 (21% identical), IL20 (20% identical), IL19 (18% identical).
Diseases named in the same sentence as IL26 in open-access papers:
IL26 is named in the same sentence as 122 diseases in open-access papers, as found by Europe PMC text mining. Sharing a sentence is not in itself a finding about the gene and the disease. The quoted sentences say what the papers report.
psoriasis (32 papers, 2010 to 2025). An autoimmune condition characterized by red, well-delineated plaques with silvery scales that are usually on the extensor surfaces and scalp. "The pathophysiological relevance of IL-26-DNA complexes is supported by elevated levels found in patients with autoimmune diseases, including psoriasis, SLE, and anti-neutrophil cytoplasmic antibody-associated vasculitis (AAV)." (PMID 41516201, 2025). "Elevated systemic levels and locally increased expression of IL26 have been reported in chronic inflammatory diseases like Crohn’s disease, rheumatoid arthritis, SpA, psoriasis and ANCA-associated vasculitis." (PMID 38799447, 2024). "IL-22, IL-20, IL-26 and IL-18 have all been implicated in inflammatory conditions such as Crohn's disease and Psoriasis in humans." (PMID 20950493, 2010). "Neutrophil-derived IL-26 triggers hallmark genes of autoinflammation including IL-1 cytokines and neutrophil recruiting chemokines, thereby contributing to pustule formation and disease activity in psoriasis." (PMID 38448036, 2024). "Moreover, elevated levels of circulating and tissue-associated IL-26 are reported in Th17 cell-mediated autoimmune diseases, such as Crohn's disease, RA, psoriasis, and AAV." (PMID 30809226, 2019). "IL-26 is a member of the IL-10 family, which has diverse antimicrobial functions and has been implicated in the pathology of lymphatic filariasis, atopic dermatitis, and Crohn’s disease, as well as in mediating Th17-associated diseases such as rheumatoid arthritis and psoriasis." (PMID 38792803, 2024). "Collectively, these findings indicate that IL-26 contributes to psoriasis through multiple mechanisms, potentially leading to pustular disease manifestations." (PMID 41516201, 2025). "Increasing evidence implicates IL-26 in the development of several chronic conditions, such as psoriasis, rheumatoid arthritis, inflammatory bowel disease, asthma, and various types of cancer." (PMID 41516201, 2025). "Upon degranulation, neutrophil-derived IL-26 plays a central role in disease exacerbation, challenging the previously held notion that Th17 cells are the primary source of IL-26 in psoriasis." (PMID 41516201, 2025). "Further studies have shown that IL-26-producing Th17 cells can comprise up to 30% of T lymphocytes infiltrating the lesions in psoriasis patients." (PMID 41516201, 2025). "IL-26, an antimicrobial cytokine belonging to the IL-10 family, is expressed in psoriasis, yet the mechanisms by which it contributes to the pathogenesis of the disease are not well understood." (PMID 38448036, 2024). "The signature also correlated with the high levels of IL-26 protein, but not with the expression levels of IL-17A in the lesions, indicating that IL-26 represents a key driver of autoinflammation in psoriasis and pustular disease activity." (PMID 38448036, 2024). "By investigating pustular forms of psoriasis, we show that human neutrophils constitutively express IL-26 and abundantly release it from granular stores upon activation." (PMID 38448036, 2024). "Here, we demonstrate that IL-26 is highly expressed in pustular forms of psoriasis when compared with PV and show that it represents a key driver of autoinflammation and disease activity." (PMID 38448036, 2024). "By comparing psoriasis subtypes, we identify a central role of IL-26 in driving and amplifying neutrophil-rich autoinflammation of the skin." (PMID 38448036, 2024). "IL-26 protein was detected in both plaque and pustular forms of psoriasis, but its expression was significantly higher in pustular forms." (PMID 38448036, 2024). "Despite the lower number, we found pseudotime trajectories between IL26+ and these IL17A+ T cells, indicating that the skin transition from IL26+ TH17 intermediates to IL-17A producers is a general principle that preferentially occurs in psoriasis." (PMID 37391412, 2023).
psoriasis (continued). "Th17-derived proinflammatory cytokines (IL-17A, IL-17F, IL-21, IL-22, and IL-26) have a critical role in the pathogenesis of several autoimmune diseases such as psoriasis, multiple sclerosis, rheumatoid arthritis, and inflammatory bowel disease." (PMID 37495626, 2023). "Then, to investigate the mechanism of TGF-β induction, we stimulated healthy keratinocytes (NHEK) in vitro with a number of cytokines characterizing the psoriasis microenvironment including IL-1β, IL-6, IL-17A, IL-19, IL-22, IL-23, IL-26, and IFN-γ." (PMID 37391412, 2023). "We found similar IL26+ spots in the dermis of AD and psoriasis, but high numbers of epidermal IL26+ spots only in psoriasis." (PMID 37391412, 2023). "TGF-β1 then conditions infiltrating IL-26+ TH17 to mature into IL-17A-producing cells, suggesting a unique tissue control of pathogenic T H17 cells in psoriasis via epithelial crosstalk." (PMID 37391412, 2023). "One of the sources of IL-17A in psoriasis is Th17 cells, then they are stimulated to secrete further cytokines by IL-23, which include (besides IL-17A): IL-17F, IL-21, IL-22, IL-26, and TNF-α." (PMID 36226313, 2022). "Other proinflammatory cytokines, including IFN-γ, TNF-α, IL-1β, IL-6, IL-22, IL-26, IL-29, or IL-36, have also been reported to play important roles in the development of psoriasis." (PMID 35313642, 2022). "Increasing evidence suggests that excessive IL-26-induced neutrophil infiltration into the area of inflammation is detrimental to mice with psoriasis-like skin lesion and sepsis." (PMID 35463017, 2022). "Elevations in IL-26 are noted in individuals with rheumatoid arthritis, Behçet’s disease (BD), atopic dermatitis (AD), psoriasis, asthma, and IBD, implicating this cytokine in the development of chronic inflammatory and autoimmune disorders." (PMID 35463017, 2022). "Serum concentrations of IL-26 are reportedly increased in patients with Crohn’s disease, psoriasis, and rheumatoid arthritis." (PMID 34572149, 2021). "IL-26 was expressed in psoriasis patients in combination with the IL-26 receptor, IL-10RB, and IL-20RA expressed by keratinocytes." (PMID 32290250, 2020). "The expression of IL-26 has been previously reported in the inflamed colonic lesions of patients with Crohn's disease and in skin lesions of patients with psoriasis." (PMID 23055831, 2012). "Anti-IL-26 therapy has been proposed for other inflammatory diseases, such as psoriasis and IBD90." (PMID 40383833, 2025). "Interestingly, high numbers of IL26+ cells were also found in AD lesional skin, similar to psoriasis." (PMID 37391412, 2023). "IL-26 is elevated in patients with chronic rheumatic diseases, such as rheumatoid arthritis, spondylarthropathies, or vasculitis, as well as Th17-mediated inflammatory skin diseases, such as psoriasis and atopic dermatitis." (PMID 34054830, 2021). "An accumulation of IL-26 has been reported in psoriasis lesions." (PMID 30809226, 2019). "Moreover, IL-6, IL-21, IL-22, IL-26, and IL-29, which participate to the amplification and maintenance of the inflammatory loop in psoriasis, all signal via STAT3." (PMID 29316631, 2018). "IL-26–transgenic mice rapidly develop a psoriasis-like skin phenotype upon topical imiquimod treatment via the induction of chemokines known to drive neutrophil recruitment to the skin, suggesting a possible link between IL-26 and autoinflammation in psoriasis." (PMID 38448036, 2024). "The precise mechanism by which IL-26 participates in the pathogenesis of psoriasis is unknown." (PMID 38448036, 2024). "Our finding also suggests that blocking IL-26 may be a beneficial approach to intervene in conditions which manifest exaggerated IL-17A responses in epithelial tissues including TH17 diseases such as psoriasis." (PMID 37391412, 2023).
psoriasis (continued). "Because psoriasis is associated with increased lesional TGF-β and IL-17A expression, we next sought to determine whether IL17A+ producing T cells in psoriatic skin differentiate from IL26+ TH17 intermediates and whether this process is driven by TGF-β." (PMID 37391412, 2023). "Since the FGF-FGFR1 axis is essential for the development of TrkA-positive unmyelinated neurons that transmit pain and itch sensations, IL-26 may play a role in the sensory neuronal development by promoting the expression of these FGFs during the pathogenesis of psoriasis." (PMID 33182442, 2020). "IL-26+ T cells are enriched in inflamed tissues in inflammatory bowel disease (IBD), RA, psoriasis, and chronic lung conditions." (PMID 41516201, 2025). "We examined the expression of cytokines previously reported to be involved in psoriasis, and found that IL17A, IL26, and CXCL13 were specifically expressed by CD8+ TRM17 and Cycling CD8+ TRM17." (PMID 41162356, 2025). "We examined the expression of cytokines previously reported to be involved in psoriasis, and found that IL17A, IL17F, IL26, CCL20, CXCL13, IL22, and IL23R were specifically expressed by Tc17 cells." (PMID 37308489, 2023). "The same feed-forward stimuli are observed in psoriasis, where TNF-α, IL-26, and IL-29 are induced by IL-17, resulting in maintaining barrier dysfunction and dysregulation." (PMID 38139369, 2023). "Here the authors establish a role for IL-26 in the generation of IL-17A producing Th17 CD4+ T cells and suggest it involves epithelial cross talk in skin lesions of psoriasis patients." (PMID 37391412, 2023). "This agreed with the findings of other studies, including that IL-26 enhances the proliferation and tube formation of vascular endothelial cells via the Akt, ERK, and NF-κB pathways in a psoriasis-like murine model." (PMID 31831038, 2019). "IL-26 mRNA is highly expressed in cutaneous biopsies of patients with primary cutaneous T-cell lymphomas (CTCL), at levels similar to patients with psoriasis." (PMID 30809226, 2019). "A study with anti-IL-26 monoclonal antibodies has shown suppression of inflammation in mouse models of psoriasis without impairing IL-26’s antimicrobial activity." (PMID 41516201, 2025). "Having shown that AD contains similar high numbers of IL26+ TH17 intermediates but lower expression levels of epidermal TGF-β1 and reduced numbers of IL17A+ cells when compared to psoriasis, we sought to compare the location of IL-26 expression in both diseases using spatial transcriptomics." (PMID 37391412, 2023). "Th17 cells exert an effect by secreting IL-17A, IL-17F, IL-26, and TNF in psoriasis, forming a feedforward inflammatory network with KCs, activating STAT-1 and NF-κB signaling pathway, and inducing keratinocytes (KCs) to secrete several pro-inflammatory factors." (PMID 32377228, 2020). "Interestingly, adaptive T-cell-derived cytokines IL17A, IL17F, IL17C, IL26, IFNG, IL4, and IL10 show comparable levels in skin biopsies from paradoxical and classical psoriasis." (PMID 29295985, 2018). "Some Th17 cells isolated from psoriasis patients, and, to a lesser extent, Th1 cells, but not Th2 and regulatory T cells, express IL-26 mRNA." (PMID 23055831, 2012). "Strikingly, the majority of IL26+ T cells in both nonlesional and lesional skin of psoriasis patients as well as in healthy skin expressed the TRM marker CD103 (ITGAE), indicating that IL26+ TH17 intermediates in the skin derive from skin-resident rather than circulating T cells." (PMID 37391412, 2023). "Moreover, in some dermatological diseases, such as psoriasis, IL-26 has been found more highly expressed in lesions than in normal skin, proving an important function in regulating the innate immunity of epithelial cells." (PMID 28289419, 2017). "The IL-26-mediated induction of TGF-β1 appears to be a general principle, but it preferentially occurs in psoriasis and not AD, despite the presence of similar numbers of IL-26+ TH17 cell intermediates in the dermis." (PMID 37391412, 2023).
rheumatoid arthritis (20 papers, 2012 to 2025). A chronic, systemic autoimmune disorder characterized by inflammation in the synovial membranes and articular surfaces. "Genetic variation of IL-26 also affects the susceptibility of women with rheumatoid arthritis." (PMID 32290250, 2020). "For example, interleukin 26 activates the NF-κB pathway to promote macrophage polarization towards M1 and ameliorate rheumatoid arthritis." (PMID 39851515, 2025). "Elevated expressions of IL-26 have been documented in a series of chronic inflammatory and autoimmune disorders, including Crohn’s disease and rheumatoid arthritis." (PMID 39431054, 2024). "For example, Lin and colleagues illustrated that IL-26 expression was increased in the synovium of rheumatoid arthritis and that IL-26 promoted macrophage differentiation from CD80+ M1 macrophages, concomitantly activating the NF-κB pathway." (PMID 39511608, 2024). "IL-26 expression is increased in the serum and synovial fluid of patients with inflammatory arthritis, rheumatoid arthritis, spondylarthritis, and psoriatic arthritis." (PMID 34572149, 2021). "Our findings suggested the role of IL-26 in synovial macrophages of active rheumatoid arthritis and provided a new insight into IL-26 as a candidate therapeutic target in rheumatoid arthritis." (PMID 32290250, 2020). "A recent study revealed that IL-26 is abundantly expressed on synovial cells of patients with rheumatoid arthritis, especially on CD68 macrophages, and in the chemotaxis of Th17." (PMID 32290250, 2020). "IL-26 expression was upregulated in the patients with rheumatoid arthritis, hepatitis C virus (HCV) infection, inflammatory bowel disease, or asthma." (PMID 31464651, 2019). "The inflammatory cascade in the rheumatoid arthritis (RA) synovium is modulated by a variety of cytokine and chemokine networks; however, the roles of IL-26, in RA pathogenesis, are poorly defined." (PMID 31831038, 2019). "Recent observations on the IL-26 effects on monocytes from rheumatoid arthritis patients also indicated independence from the classical IL-26R." (PMID 23875025, 2013). "Recent data demonstrate an additional role for IL-26 as a proinflammatory cytokine in rheumatoid arthritis." (PMID 23875025, 2013). "Here, we have analyzed the expression and role of IL-26 in rheumatoid arthritis (RA), a chronic inflammatory disorder characterized by joint synovial inflammation." (PMID 23055831, 2012). "Human interleukin-26 induces Th17 cells, is over-expressed in rheumatoid arthritis, and is thus a promising therapeutic target in chronic inflammatory disease." (PMID 23055831, 2012). "Currently, IL-26 is believed to be involved in a variety of chronic inflammatory and autoimmune disorders diseases, including Crohn’s disease, rheumatoid arthritis, atopic dermatitis, and asthma, as elevated levels of IL-26 have been commonly observed in the development of these diseases." (PMID 39431054, 2024). "Targeting IL-26 may a potential therapeutic strategy for rheumatoid arthritis or other IL-9 plus IL-17 dominant diseases." (PMID 37108686, 2023). "In conclusion, our results support that IL-26 promotes IL-9- and IL-17-expressing macrophage and might initiate IL-9- and IL-17-related adaptive immunity in rheumatoid arthritis." (PMID 37108686, 2023). "A common polymorphic marker located 3 kb 3’ of IL26 gene was significantly associated with rheumatoid arthritis in women but not in men." (PMID 23875025, 2013). "IL-26 is expressed by activated T cells and, at lower intensity, also in peripheral mononuclear blood cells, natural killer cells, and macrophage-like synoviocytes from rheumatoid arthritis joints." (PMID 23875025, 2013). "In sera and synovial fluids of rheumatoid arthritis patients, IL-26 concentrations were increased." (PMID 23875025, 2013). "Therefore, our purpose is to investigate whether IL-26 is involved in the regulation of IL-9 and IL-17 expression in rheumatoid arthritis." (PMID 37108686, 2023).
rheumatoid arthritis (continued). "Interleukin 26 (IL-26) is a new member of the IL-10 family that is highly expressed in rheumatoid arthritis (RA)." (PMID 32290250, 2020). "IL-26 has been also detected in the joints of patients suffering from rheumatoid arthritis (RA) and spondyloarthritis." (PMID 30809226, 2019). "In rheumatoid arthritis (RA), the serum concentrations of IL-26 were higher in RA patients than those of healthy subjects and dramatically elevated in RA synovial fluids compared to RA serums." (PMID 31464651, 2019). "Thus, IL-26 may serve as a promising therapeutic target in rheumatoid arthritis." (PMID 23875025, 2013). "Notably, our current results are well in line with these findings and now add to the growing body of evidence from other studies that IL-26 is involved in chronic inflammatory disorders in human patients, including rheumatoid arthritis (RA) Crohn's disease, asthma, and COPD." (PMID 35501858, 2022).